GLRX3 (glutaredoxin 3)
Diseases named in the same sentence as GLRX3 in open-access papers (continued):
Sharing a sentence is not in itself a finding about the gene and the disease.
tumor (16 papers, 2014 to 2025). "GLRX3 expression was significantly higher in tumor tissues than in normal lung, and rs4751162 G allele correlated with a significantly higher promoter activity of GLRX3 than the A allele." (PMID 34728688, 2021). "Comparative analysis revealed tumor-specific upregulation of GLRX3, IL1RN, and TNFRSF4 (p < 0.001), contrasting with downregulation of FCGRT, UBN2, and WNT5B in EC versus normal tissues." (PMID 40722666, 2025). "It is worth noting that vIRF1 can interact with lymphoid enhancer binding factor 1 (Lef1), activate circARFGEF1 transcription and regulate cell migration through the circARFGEF1/miR-125a-3p/glutaredoxin 3 (GLRX3) axis, contributing to tumor development." (PMID 40182764, 2025). "IntAct analysis revealed that BolA1/2/3 was closely associated with the GLRX3 expression in HCC, which is implicated in the regulation of the cellular iron homeostasis and tumor growth." (PMID 36017386, 2022). "GLRX3 was found to have a role in cell proliferation, metastasis, in vivo tumor formation, and tumor growth as well as in sphere formation and colony formation." (PMID 34794402, 2021). "The expression of GLRX3 was also significantly higher in tumor tissue than in normal tissue (P = 0.0003)." (PMID 34728688, 2021). "GLRX3 knockdown reduced the proportion of c-Met positive cells, and decreased tumor formation in mouse models." (PMID 34794402, 2021). "Knockdown of GLRX3 reversed vIRF1-induced cell motility, proliferation and in vivo angiogenesis, indicating that it has the characteristics of tumor genes." (PMID 33539420, 2021). "Furthermore, experiments verified GLRX3’s role in facilitating tumor cell proliferation and invasion." (PMID 39654899, 2024). "Additionally, GLRX3 was identified as a key regulatory factor in iron metabolism, and the mechanism by which GLRX3 regulates tumor cell proliferation and immune evasion was determined." (PMID 39654899, 2024). "In the TCGA cohort, GLRX3 expression was higher in advanced tumor grades and higher-stage tumors." (PMID 39654899, 2024). "Moreover, GLRX3 was also reported to be involved in tumor initiation and progression in various types of cancers via NF-κB signaling, Notch signaling, stress-induced DNA damage responses, and mTOR signaling." (PMID 34794402, 2021). "GLRX3 knockdown also reduced tumor formation and growth in vivo." (PMID 34794402, 2021). "In addition, immunohistochemical analysis of mouse tumor tissues from CFPAC-1 NC and GLRX3 K/D cells (3B10 clones) revealed cMET expression was significantly decreased in GLRX3 K/D tumor than in control." (PMID 34794402, 2021). "GLRX3 might be a putative oncogene modulating tumor growth and metastasis in NPC." (PMID 27203742, 2016). "The GLRX3 knockdown H10 clone from HPAC and B10 clone from CFPAC-1 cells showed tumor formation in only 60% (3/5) and 83.3% (5/6) of the mice, whereas the control cells showed tumor formation in 100% (5/5 and 6/6)." (PMID 34794402, 2021). "GLRX3-silenced PDAC cells showed decreased proliferation, migration, clonogenicity, and tumor formation both in vitro and in vivo." (PMID 34794402, 2021). "In addition, BolA family members and their neighborhood GLRX3 play a leading role in HCC stage and tumor grade." (PMID 36017386, 2022). "SOD1, GLRX2, PRDX6, and GLRX3 genes were also overexpressed in MM patients compared to normal plasma cells, confirming that the redox status is unbalanced in tumour vs. normal cells." (PMID 33114738, 2020). "In summary, our study shows that GLRX3 is overexpressed in NPC cells and tumor tissues." (PMID 27203742, 2016).
cancer (15 papers, 2014 to 2025). A tumor composed of atypical neoplastic, often pleomorphic cells that invade other tissues. "HPDE cell line, normal pancreatic duct cells, expressed a relatively lower level of GLRX3 compared to cancer cell lines." (PMID 34794402, 2021). "In a functional study, GLRX3 was involved in cancer cell proliferation, migration, invasion, tumorigenesis, and maintenance of CSC properties." (PMID 34794402, 2021). "Glutaredoxin 3 (GLRX3) is antioxidant enzyme, maintaining a low level of ROS, thus contributing to the survival and metastasis of several types of cancer." (PMID 27203742, 2016). "The stabilization of GLRX3 level affects several major pathways in human cancer, such as NF-κB, JNK signaling and FcepsilonRI-mediated pathway." (PMID 27203742, 2016). "Studies on NPC and OSCC have reported in common that knockdown of GLRX3 inhibited cell proliferation and decreased the migration and invasion capacity of cancer cells by suppressing the epithelial-mesenchymal transition, indicating the essential roles of GLRX3 in cancer progression." (PMID 34728688, 2021). "Immunohistochemical staining revealed strong cytoplasmic expression of GLRX3 in cancer cells." (PMID 34794402, 2021). "Of 32 cases, 20 (62.5%) showed positive GLRX3 expression in cancer tissues." (PMID 34794402, 2021). "Recently, GLRX3 expression has been correlated with human cancer." (PMID 34794402, 2021). "In silico analyses of The Cancer Genome Atlas data sets revealed consistent correlations between the expression of the transcripts encoding LRIG1 and its interactors ZBTB16 and PTPRK and inverse correlations between the transcripts encoding LRIG1 and GLRX3." (PMID 29317492, 2018). "The complicated roles of GLRX3 in cancer have remained largely undiscovered." (PMID 27203742, 2016). "From our understanding of the interaction of GLRX3 and the redox signaling in cancer cells, we hypothesized that GLRX3 may be an important molecule in NPC development and progression." (PMID 27203742, 2016). "Furthermore, the relationship between CSCs and GLRX3 in human cancer is yet to be reported." (PMID 34794402, 2021). "Hence, GLRX3 may promote cancer cell proliferation, invasion and the EMT via a PI3K/Akt pathway in NPC." (PMID 27203742, 2016). "Previous studies showed GLRX3, GLRX5, WRNIP1, THOP1, and HSCB were all regulators of various cancer occurrence and progression." (PMID 34078439, 2021). "Further, GLRX3 regulated c-MET/PI3K/AKT signaling and altered cancer stemness- and epithelial-mesenchymal transition (EMT)-related molecules." (PMID 34794402, 2021). "Glutaredoxin 3 (GLRX3) maintains a low intracellular level of reactive oxygen species (ROS), that influences survival and metastasis of cancer cells." (PMID 34944837, 2021).
infection (4 papers, 2010 to 2023). The state of being infected such as from the introduction of a foreign agent such as serum, vaccine, antigenic substance or organism. "Interestingly, our microarray data showed that the expression level of BEX2, GLRX3, GPX1 and PXCARD were down-regulated at 4 days post-infection, which is different from the up-regulated mRNA level at 8 hours post infection." (PMID 21172007, 2010).
GLRX3 also shares sentences with these, for which no sentence is quoted: cryptococcosis (3 papers); heart failure (3); colorectal cancer (2); iron deficiency (2); left ventricular hypertrophy (2); adenocarcinoma (1); bacterial infections (1); candidiasis (1); chronic heart failure (1); diabetes (1); disseminated candidiasis (1); esophageal cancer (1); glioblastoma (1); idiopathic pulmonary fibrosis (1); intervertebral disc degeneration (1); leukemia (1); Obesity (1); pancreatic adenocarcinoma (1); pancreatic ductal adenocarcinoma (1).